FAM90A3 (family with sequence similarity 90 member A3)
Synonyms: FAM90A3P
Gene: Protein-coding gene on chromosome 8 (7,264,526 to 7,267,536, forward strand). Ensembl gene ENSG00000233132.
Subcellular location (Human Protein Atlas): Nucleoplasm; Nucleoli
Homologues: Orthologues: mouse Fam90a1b (29% identical), mouse Fam90a1a (27% identical), rat Fam90a1l1 (26% identical). Paralogues in human: FAM90A11 (99% identical), FAM90A5 (99% identical), FAM90A15 (98% identical), FAM90A13 (98% identical), FAM90A14 (98% identical), FAM90A16 (98% identical), FAM90A17 (98% identical), FAM90A9 (98% identical), FAM90A24 (98% identical), FAM90A18 (97% identical), FAM90A19 (97% identical), FAM90A23 (97% identical), and 9 more.